BRCA1 (BRCA1 DNA repair associated)
Diseases named in the same sentence as BRCA1 in open-access papers (continued):
Sharing a sentence is not in itself a finding about the gene and the disease.
breast cancer (continued). "The human BACH1 gene is located on chromosome 17q22, distal to the BRCA1 gene located at 17q21, a region that is frequently altered in breast cancer." (PMID 24137204, 2013). "Through familial linkage studies in the 1990s, deleterious mutations affecting the coding regions of well-known tumor suppressor genes, i.e. BRCA1 and BRCA2, were found to associate with increased breast cancer risk." (PMID 23785296, 2013). "We performed mutation screening of all coding and 3′ and 5′ UTR sequences of BRCA1 and BRCA2 genes on ten high risk breast cancer families." (PMID 24312913, 2013). "For example, dysfunctional BRCA1 and BRCA2 diminish the efficiency of HR and germ line mutations in humans lead to a high incidence of breast cancer." (PMID 23443494, 2013). "BRCA1 is a well-known tumor suppressor gene in breast cancer and ovarian cancers, but its role in other cancer types remains elusive." (PMID 23841900, 2013). "We therefore used gene expression data from a small in-house data set of 10 BRCA1 mutant and 10 sporadic breast cancer patients as well as a publically available data set containing BRCA1 mutant and sporadic breast cancer cases." (PMID 23863842, 2013). "Taken together, these results are in agreement with our findings and in line with the observation that the majority of BRCA1 breast cancers are ER-negative." (PMID 23544013, 2013). "Expression was also detected in RNA isolated from Brca1-/- mouse mammary tumors: Bcl11a was detected in seven of eight tumors, and Sox11 was detected in two of eight tumors." (PMID 23506684, 2013). "The wt-BRCA1 breast cancer cells (MCF-7 and MDA-MB-231) were transfected with shRNAs targeting to BRCA1." (PMID 23393598, 2013). "Our findings underscore the clinical relevance of the methylation of BRCA1 promoter in Taiwanese patients with early-stage breast cancer." (PMID 23405268, 2013). "Type II carcinomas also often feature alterations of the tumor suppressor genes breast cancer 1, early onset (BRCA1) and breast cancer 2, early onset (BRCA2) and are in general genetically unstable." (PMID 23644885, 2013). "Antibody staining found Sox11 highly expressed at the invasion front in some Brca1-/- mammary tumors." (PMID 23506684, 2013). "For example, the identified rare variants in BRCA1 and BRCA2 gene all increase risk of breast cancer, and the four rare variants identified in IFIH1 gene all protect against type I diabetes." (PMID 23472070, 2013). "Mutations in some of these, like BRCA1 and BRCA2, are extremely rare, but confer high risks to breast cancer, others are common but only confer a minor increase in risk." (PMID 23383274, 2013). "In line of these findings, benzo [a] pyrene (B[a]P), an AhR ligand, also inhibited BRCA-1 expression in MCF-7 breast cancer cells and reduced these cell proliferation in a time and dose dependent manner." (PMID 25068070, 2013). "DNA samples from 3,881 breast cancer affected and 4,330 unaffected BRCA2 mutation carriers from 47 studies belonging to the Consortium of Investigators of Modifiers of BRCA1/2 were genotyped and available for analysis." (PMID 23544012, 2013). "Breast cancers with BRCA1 promoter methylation also showed decreased expression of ER and basal-like phenotype." (PMID 23405268, 2013). "A small component of the embryonic-specific mammary signature appears activated in mouse Brca1-/- tumors and in approximately 80% of human basal-like breast cancers in the datasets we examined." (PMID 23506684, 2013). "To look more specifically at BRCA1-dependent regulation of the Notch receptors and ligands in the normal breast, we used two pseudo-normal breast cancer cell lines—HME-1 h-TERT immortalized cells and spontaneously immortalized 184A1 cells." (PMID 23863842, 2013). "Germline mutations in the two major susceptibility genes for breast cancer, namely BRCA1 and BRCA2, confer a 60–85% lifetime risk of breast cancer but account for only about 20% of familial breast cancer cases." (PMID 24040146, 2013).
breast cancer (continued). "Variants such as p.R1699Q in BRCA1 or p.K3326X in BRCA2 seem to be associated with rather low, though significant, breast cancer risks." (PMID 24025454, 2013). "Hypermethylation of the BRCA1 promoter has been reported in breast cancer with links to down-regulated mRNA and protein level in tumors and cell lines." (PMID 23405268, 2013). "By comparison to the wt-BRCA1 breast cancer cells, the mutant cells HCC1937 and MDA-MB-436 expressed higher level of survivin with reduced sensitivity to paclitaxel, indicating as decreased % killed." (PMID 23393598, 2013). "TNBC shares some similar characteristics with basal-type breast cancers and BRCA1-related breast cancers." (PMID 23555923, 2013). "BRCA1 is therefore suggested to be a potential predictive biomarker in the treatment of breast cancer." (PMID 23393598, 2013). "BRCA1 and BRCA2 are clinically the most important genes associated with breast cancer susceptibility." (PMID 23941127, 2013). "The identification of BRCA1 and BRCA2 proteins and their association to breast cancer provoked numerous studies aiming to identify potential ligands of these proteins and decipher their function." (PMID 24832651, 2013). "Furthermore, we reveal sets of miRNAs associated with genes frequently amplified (ERBB2) or mutated (p16INK4a, PIK3CA and/or PTEN, E-cadherin, BRCA1) in breast cancer cell lines and thus these miRNAs may contribute to the function of these oncogenes/tumor suppressors." (PMID 23601657, 2013). "We described the first case of a BRCA1 mutation carrier affected with an ACC of the breast, a very rare histological subtype of mammary tumor." (PMID 23374397, 2013). "Especially in patients that carry germ line mutations in tumor suppressor genes such as BRCA1 or BRCA2, acquired LOH of the wild-type allele, corresponding to recessive loss-of-function mutations, will lead to hereditary breast cancer." (PMID 24004841, 2013). "In fact, the majority of BRCA1-related breast cancers express basal cytokeratins and the discovery of this status in the MBCs reported to date is in favor of the involvement of BRCA1 in the tumor development." (PMID 23374397, 2013). "Knocking down BRCA1 in breast cancer cells resulted in an increase in the expression of survivin which associated with malignant progression and drug resistance." (PMID 23393598, 2013). "Nevertheless, sporadic breast cancers represent up to 90% of breast cancers and are often characterized by decreased BRCA1 expression at mRNA and protein levels." (PMID 23805307, 2013). "For example, linkage analysis of non-BRCA1 breast cancer families with a case of male breast cancer, led to the discovery of the BRCA2 locus." (PMID 23383274, 2013). "Most currently known breast cancer predisposition genes play a role in the repair of DNA double-strand breaks by homologous recombination: BRCA1 and BRCA2, associated with a high risk of breast cancer, and BRIP1 and PALB2, associated with a moderate risk." (PMID 24139550, 2013). "We documented activation of embryonic genes in mammary tumors from mice in which Brca1-/- was inactivated in either luminal progenitor cells or basal cells." (PMID 23506684, 2013). "Our data also support the emerging view that non-BRCA1/2 hereditary breast cancer families have a very heterogeneous genetic basis." (PMID 23383274, 2013). "Germline mutations in BRCA1 and BRCA2 are detected in up to 28% of these breast-cancer families; however, it is expected that mutations still remain undetected by the currently used screening methods." (PMID 23704984, 2013). "Wild-type BRCA1/2 breast cancer cells (i.e., MCF-7 and ZR-75-1 lines) were genetically manipulated to downregulate ATM expression then assayed for cytostaticity/cytotoxicity upon treatment with PARP inhibitors, olaparib and iniparib." (PMID 24252502, 2013). "About 5–10% of familial breast cancers can be attributed to two autosomal dominant genes with high penetrance: BRCA1 and BRCA2." (PMID 24171172, 2013).
breast cancer (continued). "The stronger link between CtIP/RBBP8 and cancer, and specifically breast cancer, relies in its functional interaction with BRCA1 in DNA repair." (PMID 24403251, 2013). "Prospective studies in larger BRCA1-2 carrier series are needed to improve the best therapeutic strategies for this subgroup of breast cancer patients." (PMID 23326384, 2013). "Even though BRCA1 and BRCA2 account for the majority of genetic mutations found in breast cancer cases, only 5–10% of breast cancer cases result directly from specific gene mutations." (PMID 34589269, 2013). "BRCA1 and BRCA2 are classically defined as breast cancer susceptibility genes but each is also somatically altered in a number of tumor types including ovarian, prostate and colon." (PMID 24202319, 2013). "BRCA1 and BRCA2 are the two main breast cancer susceptibility genes for which mutation recognition is important to assess cancer risk and to identify more suitable treatment strategies." (PMID 23354980, 2013). "For example, the BRCA1 gene functions as a cancer suppressor, protecting both men and women from breast cancer (and in women, from ovarian cancer as well)." (PMID 25032017, 2013). "Breast cancers that harbour simultaneously high 53BP1 protein level and BRCA1 promoter hypermethylation and are the putative target population of drugs targeting DNA repair appear to be restricted to a small subgroup of TN tumours." (PMID 24191908, 2013). "We showed in this paper that the expression of PTEN and BRCA1 was downregulated in HCC1806 breast cancer cells compared with HMEC cells, and this diminished presence was negatively correlated with miR-20b expression in such cell lines." (PMID 23945289, 2013). "We recently reported that BRCA1 down-modulates the malignant behavior of breast cancer cells in regard to cell proliferation, migration, invasion and anchorage-independent growth." (PMID 23393598, 2013). "Multivariate analysis adjusted for age, lymph node metastasis, size and grade of tumor also revealed that methylation of the BRCA1 promoter was an independent prognostic marker for survival in early-stage breast cancer (OS, p = 0.027; DFS, p = 0.003)." (PMID 23405268, 2013). "The BRCA1 breast cancer tumor-suppressor plays an important role in DNA repair and genome stability and is also involved in G2/M checkpoint." (PMID 23451128, 2013). "The present study explored methylation of BRCA1 promoter and its relationship to clinical features and outcome in Taiwanese breast cancer patients." (PMID 23405268, 2013). "BRCA1 and BRCA2 were significantly associated with mammary tumours and the association was stronger to BRCA1 in malignant tumours." (PMID 23738139, 2013). "To determine if the differentially expressed miR-20b contributes to the expression of PTEN and BRCA1 in breast cancer, we further looked at the levels of their expression in breast cancer cell lines and breast cancer tissue arrays." (PMID 23945289, 2013). "BRCA1 (OMIM 113705) and BRCA2 (OMIM 600185), the two most important breast cancer susceptibility genes, are key players in DDR." (PMID 24159334, 2013). "A recent meta-analysis presented subgroup analyses considering BRCA1 and BRCA2 mutation carriers and found increased breast cancer risk for women with both alleles ≥29 repeat." (PMID 23483928, 2013). "It has been shown in prostate cancer and in breast cancer that BRCA1 and BRCA2 are indeed co-regulated in response to DNA damage." (PMID 23613873, 2013). "We constructed BRCA1(3300delA) by using BRCA1 full length as a template and both the BRCA1(3300delA) and the full length inserted vectors were stably transfected into BRCA1-defective breast cancer cells MDA-MB-436." (PMID 23393598, 2013).
breast cancer (continued). "The functional effects of BRCA1 P871L have been evaluated in breast cancer cell lines, and the different genotypes had distinctly different levels of BRCA1 protein." (PMID 23964347, 2013). "The close cross-talk between CHEK1 and BRCA1, the breast cancer tumour suppressor gene, at the G2/M checkpoint suggests the potential importance of this pathway in breast cancer." (PMID 23844225, 2013). "The Breast Cancer Linkage Consortium Genetic heterogeneity and penetrance analysis of the BRCA1 and BRCA2 genes in breast cancer families." (PMID 24711870, 2013). "Even though some women are genetically predisposed by inheriting the BRCA1 and BRCA2 genes, studies show that an elevated lifetime of estrogen exposure is also another risk factor for breast cancer." (PMID 23762568, 2013). "Testing for mutations in the BRCA1 and BRCA2 genes among high-risk breast cancer patients has become a routine practice among clinical geneticists." (PMID 23941127, 2013). "Chi-square analysis indicated that BRCA1 promoter methylation correlated significantly with triple-negative (ER-/PR-/HER2-) status of breast cancer patients (p = 0.041)." (PMID 23405268, 2013). "BRCA1 and BRCA2 genes are the most commonly mutated genes, but additional genes associated with hereditary breast cancer are emerging." (PMID 23586058, 2013). "Approximately 2% of Ashkenazi Jews carry mutations in BRCA1 or BRCA2 that confer, at age 70, an estimated risk of breast cancer of 56%." (PMID 23855721, 2013). "Inactivating mutations in cancer susceptibility genes, such as BRCA1 and BRCA2, which are inherited in an autosomal dominant pattern, are the major genetic factor associated with a high risk of breast cancer at an early age." (PMID 23469205, 2013). "For instance, women with a family history of breast or ovarian cancer with point mutations in the BRCA1 and BRCA2 genes are clinically recognized to have a high risk of developing breast cancer." (PMID 24358278, 2013). "We conclude that several signature components identified in our cancer dataset analysis are highly embryonic enriched, expressed at sites of active tissue remodeling in vivo during embryonic mammary development and in many Brca1-/- mammary tumors." (PMID 23506684, 2013). "It was evaluated that dislocation of the cytoplasmic BRCA1 protein in breast cancer cells, is related to the occurrence and metastasis of breast cancer and is expressed in cytoplasm of breast cancer of both younger and elder people." (PMID 23659667, 2013). "According to previous studies, ∼70% of breast cancer cases exhibit the correlation between the BRCA1 gene immune group and TNBC." (PMID 23426861, 2013). "Interestingly, human germ line mutation of BRCA1 has been shown to stimulate luminal-to-basal tumor formation by affecting the luminal progenitor cell pool and luminal cell fate, exemplifying a consequence of the involvement of breast cancer susceptibility variants in MEC differentiation." (PMID 23785296, 2013). "Based on its interactions with BRCA1, the BACH1 gene is considered a potential breast cancer susceptibility gene." (PMID 24137204, 2013). "Epidemiological evidence implicates that Chk2 and BRCA1 are in the same breast cancer prevention pathway, which is supported by the molecular process controlled by their interaction." (PMID 23388117, 2013). "Although BRCA1/2 mutations can incite genomic instability and are strong predictors of breast cancer, SATB1 abnormality is unrelated to BRCA1/2 mutations indicating that SATB1 affects DNA repair in a manner which is independent of BRCA1/2." (PMID 23326301, 2013). "High-penetrance breast cancer susceptibility genes, such as BRCA1 and BRCA2, have low mutation rates and therefore explain only a small fraction of breast cancers in the general population." (PMID 23565189, 2013). "Instead, we selected to study with more suitable BRCA1-defective breast cancer cells (HCC1937 and MDA-MB-436) and shRNA knocked down." (PMID 23393598, 2013).
breast cancer (continued). "ER+BRCA1-related breast cancers appear to be a unique group and efforts should be made to identify the individuals for whom estrogen-modifying agents are likely to be particularly effective." (PMID 24137399, 2013). "A greater sensitivity to cisplatin with decreased BRCA1 mRNA expression and a greater resistance to the paclitaxel with increased BRCA1 mRNA expression was observed in breast cancer cell lines." (PMID 23497550, 2013). "BRCA1 was also been reported to be related with the sensitivity of Topo1 poison in a study of mice model with mammary tumors." (PMID 23517622, 2013). "Germline mutation of BRCA1 frequently leads to hereditary breast and ovarian cancer (HBOC) syndrome, which accounts for 5% to 7% of all breast cancer cases." (PMID 23945289, 2013). "This is further substantiated in a mouse model of familial breast cancer described by Shakya and colleagues that generated mice with a BRCA1S1598F/S1598F background, a mutation that disrupts the interaction of BRCA1's BRCT domain with BACH1." (PMID 24832651, 2013). "Women bearing an alteration in BRCA1 or BRCA2 develop during their lifespan a breast cancer in 50–80 % of cases and an ovarian cancer in 20–40 % of cases (carriers of BRCA1 mutation) or in 10–20 % of cases (carriers of BRCA2 mutation)." (PMID 23354980, 2013). "For example, BRCA1 can inhibit progesterone receptor (PR) activity in the PR-positive human breast cancer cell line T47D and repress estrogen receptor-alpha activity in MCF-7 cells." (PMID 24321281, 2013). "In summary, we found that PALB2 mutations occur with a prevalence of 1.5% in a population of BRCA1/2-negative breast cancer patients specifically selected from a personal and/or familiar history of pancreatic cancer." (PMID 23935836, 2013). "The aim of the current study was to examine the prevalence and clinical relevance of BRCA1 promoter methylation in Taiwanese women with breast cancer." (PMID 23405268, 2013). "Rare deleterious mutations in other genes of this pathway, including BRCA1 and BRCA2, confer a high risk of breast cancer." (PMID 23544014, 2013). "Among known predisposition genes, deleterious mutations in BRCA1 and BRCA2 confer the strongest effect on disease susceptibility and are associated with a lifetime risk of breast cancer of up to 85% for such mutation carriers." (PMID 24171766, 2013). "Examples include ASE of the APC and TGFBR1 gene which has been associated with colorectal cancer or ASE of BRCA1 and BRCA2 in breast cancer." (PMID 23383130, 2013). "Western blot analysis showed that levels of PTEN and BRCA1 were downregulated in all breast cancer cell lines examined." (PMID 23945289, 2013). "Our results indicated that promoter region of BRCA1 gene is frequently methylated in Taiwanese patients with early-stage breast cancer." (PMID 23405268, 2013). "Breast cancer tumor suppressors BRCA1, BRCA2 and PALB2 form a complex and play key roles in homologous recombination (HR), DNA double strand break (DSB) repair and cell cycle regulation following DNA damage." (PMID 23585894, 2013). "Multivariate analysis of clinical factors and BRCA1 promoter methylation in patients with early-stage breast cancer for overall survival and disease-free survival." (PMID 23405268, 2013). "In recent years there has been increased penetrance of BRCA1 and BRCA2 associated breast cancer, prompting investigation into the role of modifiable risk factors in this group." (PMID 23517070, 2013). "Erlotinib has been shown to decrease BRCA1-dependent HR by twofold in breast cancer cell lines and attenuate radiation-induced Rad51 expression (a key HR protein)." (PMID 24364026, 2013).